LGR6 (leucine rich repeat containing G protein-coupled receptor 6)
Diseases named in the same sentence as LGR6 in open-access papers (continued):
Sharing a sentence is not in itself a finding about the gene and the disease.
endometriosis (1 paper, 2021). The growth of functional endometrial tissue in anatomic sites outside the uterine body. "• Establishment of endometriosis organoid model.• LGR6 is upregulated in endometriosis organoids.• Inflammatory and cancer-associated genes/traits are found in endometriosis organoids." (PMID 33959613, 2021).
Hyperglycemia (1 paper, 2025). An increased concentration of glucose in the blood. "Knocking down LGR6 in cells blocked the beneficial effects of MaR1 on reducing ROS and inflammation, further confirming that LGR6 is essential for the actions of MaR1, reduced hyperglycemia, and slowed the pathological progression of kidney damage." (PMID 40243751, 2025).
Hypertension (1 paper, 2024). The presence of chronic increased pressure in the systemic arterial system. "To investigate the role of the receptor LGR6 in pathological hypertension, we generated LGR6 knockout (KO) mice and treated them with AngII." (PMID 38463394, 2024). "Our study demonstrates the effect of MaR1 and its receptor LGR6 during the progression of hypertension." (PMID 38463394, 2024). "In this study, we investigated the effect of MaR1/LGR6 signaling on hypertensive vascular remodeling in an AngII‐induced hypertension mouse model and further analyzed its potential mechanisms." (PMID 38463394, 2024). "Maresin‐1 ameliorates VSMC proliferation, migration, phenotype transition, and pyroptosis through LGR6, thereby alleviating vascular remodeling in hypertension." (PMID 38463394, 2024). "MaR1 activates LGR6 in VSMCs, blocking intracellular Ca2+ elevation, leading to VSMC dedifferentiation and pyroptosis inhibition, therefore alleviating vascular remodeling and hypertension progression." (PMID 38463394, 2024).
hypertrophic cardiomyopathy (1 paper, 2025). A condition in which the myocardium is hypertrophied without an obvious cause. "In this study, we observed that Lgr6 was downregulated in the myocardial tissues of PO model mice and patients with hypertrophic cardiomyopathy." (PMID 40211903, 2025).
injury (1 paper, 2022). Damage inflicted on the body as the direct or indirect result of an external force, with or without disruption of structural continuity. "LGR6+ve ASMCs are very important during airway regeneration, promoting airway differentiation of epithelial progenitors through WNT-FGF10 cooperation, and the depletion of these cells caused major defects in regeneration following naphthalene-induced lung injury in vivo." (PMID 35328508, 2022).
metastatic cancer (1 paper, 2017). A carcinoma which has spread from the original site of growth to another anatomic site. "Loss of TRF2 and Terc expression resulted in telomere DNA damage, severely depleted CD34 + and Lgr6+ cancer stem cells, and induced terminal differentiation of metastatic cancer cells." (PMID 29113290, 2017).
neuroblastoma (1 paper, 2023). Neuroblastoma (NB) is the most common solid, extracranial childhood tumor. "The neuroblastoma cell line SK-NA-S only expresses LGR5 as shown by us and others, and RNA-seq data showed no or little expression of LGR4, LGR6, RNF43, or ZNRF320,35." (PMID 37402772, 2023).
Obesity (1 paper, 2020). Accumulation of substantial excess body fat. "MaR1 administration partially reverses the inhibitory effects of obesity on colonic Lgr6 levels, suggesting the potential involvement of LGR6 in the anti-inflammatory properties of MaR1 in the inflamed colon of obese mice." (PMID 32751593, 2020).
osteoarthritis (1 paper, 2022). A noninflammatory degenerative joint disease occurring chiefly in older persons, characterized by degeneration of the articular cartilage, hypertrophy of bone at the margins and changes in the synovial membrane. "In addition, enhanced expression of LGR5 and RSPO2 was detected in chondrocytic differentiation of human chondrocytes in advanced stage of osteoarthritis, while elevated expression of LGR6 and RSPO1 was observed in osteogenic differentiation of SaOS‐2 cells." (PMID 35668632, 2022).
Sepsis (1 paper, 2025). Sepsis is defined as life-threatening organ dysfunction caused by a dysregulated host response to infection. "Targeting LGR6 has potential to resolve inflammation, enhance macrophage phagocytosis, and promote tissue repair in sepsis." (PMID 40761792, 2025). "Furthermore, we identified N-acetylputrescine, a potential sepsis biomarker with high abundance in Proteus (log2FC = 9.62), as a candidate binding metabolite for the Tier 1 sepGIK LGR6." (PMID 40761792, 2025).
squamous cell carcinoma (1 paper, 2020). A carcinoma arising from squamous epithelial cells. "Since MYCT58A expression drove increased expression of the stem cell markers Lin28B, Lgr6, and Sox2 in this model, we also asked if the expression of these genes correlated in human squamous cell carcinomas." (PMID 32895364, 2020).
subarachnoid hemorrhage (1 paper, 2025). A serious neurological disorder characterized by intracranial hemorrhage into the subarachnoid space. "According to recent research, in a rat model of subarachnoid hemorrhage, Maresin 1 activates LGR6 to reduce neuroinflammation via the CREB/JMJD3/IRF4 pathway." (PMID 40227207, 2025).
triple-negative breast carcinoma (1 paper, 2025). An invasive breast carcinoma which is negative for expression of estrogen receptor (ER), progesterone receptor (PR), and human epidermal growth factor receptor 2 (HER2). "In triple-negative breast cancer (TNBC), LGR6 mediates stemness, chemoresistance, and metastasis." (PMID 40821817, 2025).
tumor (38 papers, 2009 to 2026). "The receptor LGR6 expression exhibited variable expression across patients and tumor grade, suggesting an underlying heterogeneity." (PMID 35619544, 2022). "While ablation of LGR6-positive cells has detrimental consequences for the regeneration of skin, nails and bone, leading to defective tissue repair, increased LGR6 expression has been associated with tumour proliferation and invasion." (PMID 34943945, 2021). "Conversely Lgr6 and Lrig1 tumours have associated stromal inflammation while Lgr5 tumours do not." (PMID 29807713, 2018). "This SOX2-driven stemness state also appears to be activated in tumours derived from the LGR6+ population in the DMBA/TPA model." (PMID 41507151, 2026). "In contrast to several studies suggesting LGR6-receptor as a stem cell marker and tumor suppressor, we barely found LGR6 expression in ENS cells during proliferation in vitro." (PMID 40998011, 2025). "LGR6 is also expressed in tumor cells that are more mature, the difference being that CSC express higher levels than more mature cancer cells." (PMID 38715790, 2024). "LGR6, as a tumor suppressor, belongs to the rhodopsin-like seven-transmembrane domain receptor superfamily and is a high-affinity receptor of R-spondins with potential functions." (PMID 34336645, 2021). "Lastly, Lgr6 and Sox9 mRNA appeared to be more expressed in malignant forms of specific tumour types (TE), indicating a potential role of the two molecules in cancer progression and as prognostic markers." (PMID 32397255, 2020). "In line with this, Lgr6 was expressed in both HF and epidermal skin tumours of our study, indicating a potential common cell of origin of these tumours, that are then able to differentiate into different lineages." (PMID 32397255, 2020). "Lgr6 mRNA was detected in all the HF tumour types, with the highest expression values in TB and TL (inferior type)." (PMID 32397255, 2020). "In accordance with that, both Lgr5 and Lgr6 showed the highest mRNA expression levels in this tumour type in dogs (present results) and humans." (PMID 32397255, 2020). "To confirm increased stem cell gene expression in these hyperplastic regions, we also assessed the mRNA level of Lin28B, CD34, Lgr6, and Sox2, which can serve as markers for stem-like tumor cells in skin squamous cell carcinoma." (PMID 32895364, 2020). "Although LGR6 expression was observed in the tumour burden in earlier (I and II) and later (III, IV and metastatic) stages, a stage-related enrichment in LGR6+ cells was found during cancer development." (PMID 31236545, 2019). "The detected tumour burdens expressed lung-specific markers, including SP-C and CC- 10, and showed only partially LGR6 expression." (PMID 31236545, 2019). "Intriguingly, the different tumours induced by stabilizing β-catenin in Lgr5+, Lgr6+, and Lrig1+ epithelial cells exhibit both similarities and differences in stromal composition." (PMID 29807713, 2018). "This review will focus on the regulation of epithelial stem cells by LGR5 and LGR6 and the contribution of this signaling pathway to tumor formation and chemoresistance." (PMID 29416699, 2018). "In this case the Lgr6 progeny would make up the complete tumor mass, staining completely blue from X-gal cleaved by β-galactosidase, coded for by the LacZ gene." (PMID 27880932, 2016). "If tumors arose in the lineage of initially abundantly present Lgr6+ stem cells this should have resulted in LacZ+ tumor masses." (PMID 27880932, 2016). "We only found some sporadic Lgr6+ cells (EGFP+) in the bulk of 1 tumor (out of 6 tumors from 4 mice) from the UV carcinogenesis group (data not shown)." (PMID 27880932, 2016). "Expression of Lgr6, a SC marker for the IR, was also decreased in tumours isolated from both K14ΔNLef1 and K15ΔNLef1 animals." (PMID 25608467, 2015). "Mechanistic studies have demonstrated that LGR6 is a high affinity receptor for R-spondins 1–3 and potentially functions as a tumor suppressor." (PMID 24708840, 2014).
tumor (continued). "On the other hand, the finding that LGR6 has positive effects on Wnt/β-catenin signaling and cell migration appears to be inconsistent with a tumor suppressor function." (PMID 22615920, 2012). "The notion that LGR6 is expressed specifically in a population of stem cells that can give rise to all cell lineages of the skin and that cancer often originates from stem cells suggests that LGR6 may be the underlying receptor for the tumor suppressive role of RSPO1." (PMID 22615920, 2012). "LGR6 is a high affinity receptor for R-spondins 1–3 and potentially functions as a tumor suppressor despite its positive effect on Wnt/β-catenin signaling." (PMID 22615920, 2012). "This suggests that a differentiation-committed cell that has regained stemness potential, such as basal IVL+ or follicular LGR6+, could be the cell of origin in these tumours." (PMID 41507151, 2026). "Taken together, we present new evidence in PDAC that LGR6 might be a novel WNT target gene in this tumor." (PMID 37770230, 2023). "Furthermore, they activated tumorigenic K-RasG12D, and deleted the tumor suppressor WD and F-box repeat domain, in Lgr6+ cells to assess the tumor-initiating capacity of cells in a second tumor model." (PMID 36140088, 2022). "However, two independent studies have also identified tumor-suppressive functions of LGR6, suggesting LGR6 oncogenic and tumor-suppressive functions are likely to be tumor and tissue-type dependent." (PMID 35204808, 2022). "Indeed, we observed very strong expression of RSPO4 and LGR6 in the mesenchymal cells and epithelial components of the tumor, respectively." (PMID 34099859, 2021). "Our studies suggest a disruption in the p38α MAPK/mir-17-92 network, that enhances Wnt pathway activity, could be responsible for the selection of malignant LGR6+ tumour cells." (PMID 31236545, 2019). "LGR6 is enriched in tumour cells during adenocarcinoma progression." (PMID 31236545, 2019). "Therefore, classic quiescent stem cells have been studied as potential tumor-initiating cells, as well as more recently discovered actively dividing stem cells (either Lgr5+ or Lgr6+)." (PMID 29896477, 2018). "Thus, the TPA tumor-promoting regimen appears to have had a totally different effect on Lgr6+ stem cells and their progeny in the IFE than the UV regimen." (PMID 27880932, 2016). "Injecting in mice with already established tumors and subsequent tracing for 2-3 weeks would enable determining whether Lgr6+ stem cells in the tumor were driving the growth." (PMID 27880932, 2016). "Interestingly, RSPO1, a high affinity ligand of LGR6, also appears to function as a tumor suppressor." (PMID 22615920, 2012). "LGR6 could detect CC patients at risk in stage I but not in stage II, indicating that the size of the primary tumor does not necessarily reflect the aggressivity of the cancer." (PMID 38715790, 2024). "Both Lgr5 and Lgr6, together with the other member of the same receptor family, namely Lgr4, are recognized mediators of the Wnt signalling pathway, that is activated in human HF tumours, especially TB, and probably in canine TB as well, as indicated by the presence of numerous positive nuclei." (PMID 32397255, 2020). "The high expression of LGR5 and LGR6 mRNA in HGSOCs allows them to be constantly stimulated by WNT signaling, which leads to uncontrolled cell growth and tumor development." (PMID 40836974, 2024). "XCL1 or CD160 expression co-localised with LGR6 expression, and co-expression within tumours was seen in 16.3% (16/98) of our cohort for XCL1 and LGR6, and 27.8% (25/90) for CD160 and LGR6." (PMID 39419971, 2024). "In order to assess their stem-like identity and the tumorigenic potential, the molecular profile of sorted LGR6+ tumour cells, from different stages of human lung ADC, was analysed and compared to LGR6- cancer cells." (PMID 31236545, 2019).
tumor (continued). "The different tumor types also had different effects on CD26 expression: CD26 expression was unchanged when LGR5+ cells were targeted, was upregulated on targeting of LGR6+ cells, and was downregulated by targeting LRIG1+ cells." (PMID 26771241, 2016). "At least four genes (CD109, CHD5, LGR6, and ICAM5) displayed a different level of methylation, depending on the tumor location." (PMID 19750230, 2009). "LGR6 is useful as a complementary biomarker in mRNA analysis of LNs of patients with CC but not for analysis of the primary tumor." (PMID 38715790, 2024). "LGR6 expression had no obvious correlation with clinical‐pathological variables, including sex (P = .183), age (P = .181), tumor node metastasis category (T, P = .478; N, P = .576), or clinical stage (P = .112)." (PMID 31917882, 2020). "Serial transplantation of Itgav+ tumor cells failed to generate CD34+ or Lgr6+ cancer cells as shown by flow cytometry." (PMID 29113290, 2017). "In one tumor from a haired mouse subjected to chemical carcinogenesis and traced from the start of the experiment, we found more abundant Lgr6 progeny at the outer rim of the tumor but not in the tumor bulk." (PMID 27880932, 2016). "Although the inter-tumoral IFE clearly showed Lgr6 progeny, none of the UV- or chemically induced tumors (n = 22 and 41, respectively) appeared to be clonal expansions of Lgr6+ stem cells; i.e. no Lgr6+ cells or progeny in the proliferating tumor bulk." (PMID 27880932, 2016). "Lgr6+ cells did not appear to become the tumor-initiating cells (TICs) in UV carcinogenesis, nor in two-stage chemical carcinogenesis." (PMID 27880932, 2016). "The absence of Lgr6+ cells as driver cells in the tumor was further confirmed by starting lineage tracing after tumors had developed." (PMID 27880932, 2016). "One of the genes, LGR6 (Leucine-Rich Repeat Containing G Protein-Coupled Receptor 6) regulates the phosphoinositide 3-kinase/AKT signaling pathway and plays a tumor-promoting role in CRC development indicating that it might be a potential diagnostic and prognostic biomarker for CRC." (PMID 32711505, 2020). "Importantly, LGR5 and LGR6, and their ligands RSPO1–4, are upregulated in several cancers, lending support to the idea that elevated Wnt signaling may be a driver of tumor formation." (PMID 29416699, 2018). "Our data show that Lgr6+ cells are not major tumor-initiating cells in skin carcinogenesis." (PMID 27880932, 2016). "Since Lgr6+ stem cells and their progeny were absent in the tumor bulk, we posed the question whether EGFP and LacZ expression could have been silenced by aberrant methylation of the promoters involved." (PMID 27880932, 2016). "Interestingly, the tumor sample containing the LGR6 insGRS mutation also has mutation in APC but not in β-catenin, suggesting that the action of LGR6 does not depend on the genetic status of β-catenin." (PMID 22615920, 2012). "However, dermal CD26 expression is upregulated in the stroma of Lgr6 but not Lgr5 or Lrig1 tumours." (PMID 29807713, 2018). "Our group could not detect any appreciable presence of Lgr6+ cells in tumors and only some sporadic remnants of progeny deep into the differentiated compartments, i.e., no indication that Lgr6+ cells were TICs or drove tumor growth." (PMID 29896477, 2018). "The tumors themselves were devoid of Lgr6+ stem cells (no EGFP detected) and their progeny, except for some LacZ positivity in rare and small patches in terminally differentiated parts of the tumors – most likely inclusions of normal cells in the tumor mass." (PMID 27880932, 2016).